PKM (pyruvate kinase M1/2)
Diseases named in the same sentence as PKM in open-access papers (continued):
Sharing a sentence is not in itself a finding about the gene and the disease.
colon carcinoma (110 papers, 2013 to 2025). "In contrast, miR-124 and miR-137 accelerate the conversion of PKM pre-mRNA to PKM1 in colon cancer cells by inhibiting hnRNPA2." (PMID 38785973, 2024). "The HOXB-AS3 peptide can competitively bind to the arginine residue in the hnRNPA1 RGG motif and inhibit the binding of hnRNPA1 to PKM, which further down-regulates the level of PKM2 and inhibits the metabolism reprogramming process of colon cancer cells." (PMID 38785973, 2024). "LncRNA-HOXB-AS3 peptide suppressed colon cancer (CRC) growth through blocking hnRNPA1-mediated PKM splices, thereby inhibiting the formation of PKM2 and suppressing the reprogramming of the glucose metabolism." (PMID 36072431, 2022). "SRSF3 regulates the cell growth and maintenance energy metabolism of colon cancer cells through PKM splicing." (PMID 35715407, 2022). "Suppress colon cancer aerobic glycolysis by blocking hnRNP A1 dependent PKM splicing and PKM2 formation." (PMID 34888249, 2021). "This peptide inhibits tumorigenesis through the blockage of PKM splicing, mir-18a processing, and PKM2 formation, causing metabolic reprogramming in colon cancer cells." (PMID 34827671, 2021). "Recently, we reported that miR-124-mediated switching of PKM isoform expression from cancer-dominant PKM2 to PKM1 disrupted the Warburg effect in colon cancer cells." (PMID 28380435, 2017). "We already reported that the PKM-splicer PTBP1 acts as an oncogene in colon tumors to establish and maintain the cancer specific energy metabolism." (PMID 28106737, 2017). "Additionally, our identification of RNF8-interacting ENO1, LDH1, PKM, PYCR, and MDH2 might provide other mechanisms underlying RNF8-regulated colon cancer progression." (PMID 35831895, 2022). "As one of the essential SFs for PKM, PTBP1 is highly expressed in two drug-resistant colon cancer cell lines (HCT-8/V and HCT116)." (PMID 38785973, 2024). "In colon cancer, the micropeptide HOXB-AS3 inhibits PKM2 isoform production and reprogrammes glucose metabolism by blocking hnRNP A1-dependent PKM splicing, miR-18a processing, and thus CRC growth." (PMID 38622617, 2024). "Furthermore, kaempferol may play an anti-colon cancer role by regulating the expression of MMP1, MMP2, and MMP9 protein, thereby increasing the expression level of miR-339-5p to mediate PKM alternative splicing reversing aerobic glycolysis in colon cancer cells." (PMID 39221164, 2024). "The overexpression of GGH in colon cancer-derived cell lines (SW48 and SW480) inhibited PKM, GLUT1, and LDHA expression and decreased the extracellular lactate content and intracellular ATP level." (PMID 36569910, 2022). "PKM is expressed in fetal tissues and cancers, and participates in the EMT process of human colon cancer cells." (PMID 35222014, 2021). "We found that POU2F1 transcripts were positively correlated with hexokinase 2 (HK2), 6-phosphofructo-2-kinase/fructose-2,6-biphosphatase 2 (PFKFB2), ALDOA, pyruvate kinase M1/2 (PKM), lactate dehydrogenase A (LDHA), G6PD, and ribose 5-phosphate isomerase A (RPIA) levels in the colon cancer tissues." (PMID 34997215, 2022). "This is exemplified in KIRC, where high expression of PKM2 and PKM-609 pair indicated favorable prognoses of patients and high expression of PKM-093 and PKM-883 pair indicated the opposite, and similar scenarios could be found in CESC, PAAD, BRCA, and colon carcinoma (COAD)." (PMID 33478099, 2021).
glioma (100 papers, 2011 to 2025). A benign or malignant brain and spinal cord tumor that arises from glial cells (astrocytes, oligodendrocytes, ependymal cells). "Trametinib (MAPK inhibitor) binds and inactivates PKM2, reducing the levels of nuclear PKM through the suppression of the PKM2/c-myc axis, blocking the glycolysis, migration, and invasion in glioma cells." (PMID 38139462, 2023). "For example, alterations in alternative splicing of the PKM, ANAX7, and MYO1B genes have been implicated in the context of glioma progression." (PMID 36171198, 2022). "Numerous groups have demonstrated that GBM express more PKM2 than normal brain, although the extent to which PKM expression and PK activity vary with respect to glioma grade has only partially and indirectly been examined." (PMID 23451252, 2013). "The present studies therefore represent the first complete analysis of PKM expression and PK activity with regard to glioma grade, and are the first to our knowledge to show grade-specific differences in PKM2 expression, but not PK activity, in glioma." (PMID 23451252, 2013). "The work presented also suggests that modulation of both PKM expression and PK activity are important for continued glioma cell growth." (PMID 23451252, 2013). "The present findings provide the first detailed picture of PKM expression and activity across a range of gliomas of different grades." (PMID 23451252, 2013). "In our examination of PKM isoform expression and PK activity in a series of over 100 astrocytomas, we found that PKM1 expression and PK activity was consistently low (relative to normal brain tissue) across as wide-range of gliomas, but that PKM2 expression increased in a GBM-specific manner." (PMID 23451252, 2013). "To address these questions we examined PKM isoform expression and PK activity in an extensive series of grade I-IV astrocytomas, and have examined the consequences of alteration of PKM expression and activity on the growth of human glioma cells." (PMID 23451252, 2013). "PTBP1 has been described as one of the key RBPs in regulating AS in neural development and known oncogenic AS gene isoforms such as PKM and USP5 in glioma." (PMID 38662454, 2024). "The results show that PKM and TPI1 are two novel genes suitable for genic expression studies on gliomas." (PMID 34573317, 2021). "Therefore, the PKM gene was used as a reference gene to measure the expression levels of genes of metabolic pathways in brain glioma biopsies of pediatric patients diagnosed with different CNS WHO grades of gliomas, because it showed the best stability ranking in the statistical analyses." (PMID 34573317, 2021). "Of these 8 genes, 6 (SULT4A1, NDRG4, GAP43, BEX1, HINT1, LZTS1) are believed to act as tumor suppressants, while the remaining two, PKM and VIPR1, have been found to be overexpressed in glioma." (PMID 28957313, 2017). "PKM2 expression, but not activity, is regulated in a grade-specific manner in gliomas, but changes in both PKM activity and PKM2 expression contribute to the growth of GBMs." (PMID 34944870, 2021). "Moreover, IDH1 wild-type gliomas displayed a significantly increased expression of glycolytic enzyme genes (LDHA, HK2, PGAM2, PGK1, PKM, TIGAR) compared to IDH1-mutant gliomas as shown in heatmaps." (PMID 33493139, 2021). "The results obtained in this study suggest that the PKM and TPI1 genes could be used as reference genes to normalize and quantify the expression of target genes in pediatric gliomas samples by RT-qPCR." (PMID 34573317, 2021). "Detection of endogenous levels of total PKM protein (including M1 and M2) also did not identify any significant difference between gp120 treated and untreated glioma cells." (PMID 30200472, 2018). "Given the differences in PKM expression and aggressiveness of GBM relative to lower grade tumors, and the link between PKM isoform expression and metabolism, we also determined if changes in PK activity were noted across glioma grades." (PMID 23451252, 2013).
glioma (continued). "Thus, the larger expression of PKM in glioma spheroids when compared with NSCs may stem from a higher expression of PKM in gliomas in general, not specifically in their CSCs' subpopulation." (PMID 24481450, 2014).
gastric cancer (84 papers, 2011 to 2025). A primary or metastatic malignant neoplasm involving the stomach. "Reports revealed that microRNA-133b could silence PKM-splicer PTBP1, leading the inhibition of growth of human gastric cancer cells." (PMID 28232943, 2017).
glioblastoma (73 papers, 2011 to 2025). The most malignant astrocytic tumor (WHO grade IV). "ENO1 has been reported to regulate the kinase activity of ERK1/2 in A549 cells, and ERK1/2 can modulate the nuclear translocation of PKM in U251 human glioblastoma cells that is necessary for PKM’s auto-regulation of expression." (PMID 28969663, 2017). "Isoform switch of PKM2 in glioblastomas, overexpression of PKM2 in most tumor types via hypomethylation near the PKM gene promoter, and its prognostic value in head and neck cancer justify the development of PKM2 inhibitors as promising anti-cancer therapeutics." (PMID 24077665, 2014). "To address this issue, we measured PKM isoform expression and PK activity in normal brain, neural progenitor cells, and in a series of over 100 astrocytomas ranging from benign grade I pilocytic astrocytomas to highly aggressive grade IV glioblastoma multiforme (GBM)." (PMID 23451252, 2013). "Brain‐specific miR‐137 and muscle‐specific miR‐206 regulate PKM expression and inhibit the Warburg effect by directly binding PTBP1 mRNA in glioblastoma and rhabdomyosarcoma, respectively." (PMID 40579921, 2025). "Pyruvate kinase M1/2 (PKM/PKM2), a glycolytic regulator, interacted with and phosphorylated Bcl-2 apoptosis regulator (Bcl-2) to upregulate its expression, suppressing apoptosis in glioblastoma cells and promoting NSCLC cell proliferation." (PMID 40508066, 2025).
liver cancer (72 papers, 2011 to 2026). An epithelial or non-epithelial malignant neoplasm that arises from the liver. "Antisense oligonucleotide-based PKM splice switching has been proposed as a targeted therapy for liver cancer." (PMID 39684755, 2024). "For example, the splicing factor SRSF3 can directly bind to LNCAROD, inducing PKM isoform switching to PKM2 and enhancing aerobic glycolysis in liver cancer cells, promoting tumor malignancy and chemotherapy resistance." (PMID 38785569, 2024). "An antisense oligonucleotide (ASO) that switches PKM splicing from tumor-promoting PKM2 to the PKM1 isoform limits aerobic glycolysis, thereby inhibiting HCC growth both in vitro and in vivo, laying the groundwork for a potential ASO-based splicing therapy in treating liver cancer." (PMID 37566009, 2023). "Thus, we further investigated whether ER stress can selectively modulate the expression of the PKM gene to PKM2 rather than PKM1 by altering the miRNA expression profile of liver cancer cells." (PMID 34786210, 2021).
pancreatic cancer (71 papers, 2012 to 2026). "Switching PKM splicing to favor PKM1 variant in drug resistant pancreatic cancer cells rescues sensitivity to gemcitabine and cisplatin, suggesting that PKM2 expression is required to withstand drug-induced genotoxic stress." (PMID 26918353, 2016). "Linc-UROD can prevent ENO1 and PKM from being degraded by proteasome by reducing the ubiquitination of ENO1 and PKM proteins, and finally enhance the glycolysis and invasion ability of pancreatic cancer." (PMID 37582735, 2023). "Calabretta's study has revealed that modulation of the pyruvate kinase gene (PKM) splicing can promote gemcitabine resistance in pancreatic cancer cells." (PMID 35046435, 2022). "We identified PLAU, LDHA, and PKM as key genes involved in pancreatic cancer hypoxia through GO/KEGG enrichment related hypoxia pathways and cox regression, established prognostic models, and studied their relationship to immune invasion through bioinformatics using R and related online databases." (PMID 37277450, 2023). "In two studies, the splicing factors PTBP1 and TRA2A were up-regulated in resistant cells and promoted resistance to gemcitabine in pancreatic cancer through AS regulation of the PKM gene, and to paclitaxel in triple-negative breast cancer through AS of RSRC2, respectively." (PMID 31943118, 2020). "Additionally, PTBP1 was demonstrated to alter the alternative splicing process of PKM to promote gemcitabine resistance in pancreatic cancer cells." (PMID 31355266, 2019). "Based on survival analysis, 6 out of 32 MMRGs (LDHA, ALDH3B1, LDHAL6B, PKM, ALDH3A1, and PGAM4) in pancreatic cancer were of survival significance." (PMID 36814901, 2023). "In pancreatic cancer, AS events of the PKM were differentially regulated and promoted the expression of the PKM2 isoform." (PMID 31552163, 2019). "In studies on pancreatic cancers, PTBP1 has been shown to regulate the spicing of the pyruvate kinase (PKM) mRNA and thereby resulting in gemcitabine resistance." (PMID 31729427, 2019). "We verified the high expression of PLAU, LDHA, and PKM in pancreatic cancer cells using qPCR in vitro, and we also discovered that the expression of PLAU, LDHA, and PKM in hypoxic pancreatic cancer cells differed from that in normal cultured pancreatic cancer cells." (PMID 37277450, 2023).
bladder cancer (69 papers, 2011 to 2026). "Using a Cox proportional regression model, we established that a 4-mRNA signature (NUP205, NUPL2, PFKFB1 and PKM) was significantly associated with prognosis in bladder cancer patients." (PMID 32467671, 2020). "Another four-gene glycolytic signature (NUP205, NUPL2, PFKFB1, and PKM) showed excellent performance in predicting the OS of bladder cancer patients." (PMID 35109912, 2022). "PKM2 was found to be the prominent isoform in bladder cancer samples, accounting for approximately 60% of PKM in the bladder." (PMID 32467671, 2020). "Additionally, RBMX inhibits aerobic glycolysis via hnRNP-A1-dependent PKM alternative splicing, and it counteracts the aggressive phenotype induced by PKM2 overexpression in bladder cancer cells." (PMID 39132499, 2024). "Thus, overexpression of genes related to glycolytic processes, such as GLUT1, GLUT3, HK2, LDHA, and PKM, is common in bladder cancer tissues and cells." (PMID 37258572, 2023). "In contrast, in bladder cancer, RBMX exhibits an oncogenic effect by inhibiting hnRNP A1-mediated PKM splicing." (PMID 40692788, 2025). "By inhibiting hnRNPA1-dependent PKM splicing and consequent PKM2 overexpression, RBMX neutralizes the aggressive phenotype of metastatic bladder cancer cells." (PMID 38785973, 2024). "In our study, we knocked down CK2α level in bladder cancer cells and then observed decrease in glucose uptake and lactate production, accompanied with low level of GLUT1, HK, PKM, and LDH." (PMID 27888634, 2016). "For instance, our data indicated that PTBP1 was not involved in the splicing regulation of MESI and PKM, which induce tumor proliferation in bladder cancer, indicating the context‐dependent nature of PTBP1 target selection." (PMID 39287090, 2024). "With low expression in metastatic bladder cancer tissues, RBMX can competitively bind to the RGG motif of hnRNPA1 and block it from combining with the lateral intron of PKM mRNA exon 9, leading to high expression of PKM1 and weakening the malignancy and progression of tumors." (PMID 38785973, 2024). "Consistently, our study found that the mRNA level of PKM was upregulated in bladder cancer tissues compared with normal tissues." (PMID 32467671, 2020).
ovarian carcinoma (61 papers, 2013 to 2026). A malignant neoplasm originating from the surface ovarian epithelium. "Based on IPA analysis, 5 proteins, namely PKM, ANXA2, LGAL3, HNRNP1A1, PRDX3 and GAPDH, were found to be associated with the apoptosis signaling pathway in A2780 ovarian cancer cell line." (PMID 35163852, 2022). "In response to an A2780 ovarian cancer cell line treated with 9-methoxycanthine-6-one, it was noted that 3 proteins, namely GAPDH, HNRNPA1 and PKM, suppressed and interfered with the anti-apoptotic protein, BCL-XL." (PMID 35163852, 2022).
prostate carcinoma (61 papers, 2013 to 2026). A carcinoma that arises from epithelial cells of the prostate gland. "Analysis indicated that the 9 hub genes (AKT1, HSP90AA1, SRC, GSK3β, VEGFR2, RHOA, ENO1, PKM, and IL-2) play roles in MF treatment by participating in signaling pathways related to prostate cancer, lipid and atherosclerosis, and insulin resistance." (PMID 40051434, 2025). "Collectively, these findings demonstrate that ZMYND11 suppresses aerobic glycolysis in prostate cancer cells by inhibiting HNRNPA1-dependent PKM splicing." (PMID 39341825, 2024). "Isoform switching in various genes (such as PKM, CXCR3 and FGR2) during cancer development has been described in several cancer types including prostate cancer, and likewise tumour-specific isoforms of known genes have been identified previously." (PMID 27683107, 2016).
Sepsis (50 papers, 2016 to 2025). Sepsis is defined as life-threatening organ dysfunction caused by a dysregulated host response to infection. "The glycolysis-encoding genes HK2 (hexokinase-2), HK3 (hexokinase-3), LDHA, and PKM (pyruvate kinase M) in the PMNs of patients with sepsis were significantly altered compared to those in the PMNs of healthy volunteers." (PMID 35090526, 2022). "Therefore, it is clear that changes in the PKM expression and activity are involved in changes in lactate concentration and can lead to sepsis, particularly SILD." (PMID 34445236, 2021). "CD38high C1 monocytes of the Sepsis group highly expressed oxidative stress related genes and glycolysis signature related genes, such as ENO1, PKM, PGK1, and LDHA, which were key glycolytic enzymes." (PMID 40145840, 2025).
cervical carcinoma (49 papers, 2013 to 2025). A carcinoma arising from either the exocervical squamous epithelium or the endocervical glandular epithelium. "In addition, LDHA, CCL4, and PKM were reported to be associated with the development, proliferation, or progression of cervical cancer cells." (PMID 36284631, 2022).
melanoma (48 papers, 2009 to 2026). A malignant, usually aggressive tumor composed of atypical, neoplastic melanocytes. "Indeed, PKM has been identified as one of the major hypoxia-induced HIF1α targets in melanocytes that significantly correlate with reduced melanoma disease-free status." (PMID 33937086, 2021).
diabetes (31 papers, 2012 to 2025). "Hexokinase 2 (HK2; FC = −3.4), succinate dehydrogenase complex, subunit C (SDHC; FC = −3.1), isocitrate dehydrogenase 1 (IDH1; FC = −1.8), and pyruvate kinase muscle (PKM; FC = 1.5) were all downregulated in individuals with diabetes." (PMID 34690929, 2021).
leukemia (28 papers, 2015 to 2026). A malignant (clonal) hematologic disorder, involving hematopoietic stem cells and characterized by the presence of primitive or atypical myeloid or lymphoid cells in the bone marrow and the blood. "Previous work has implicated PTBP1 in the regulation of glycolysis by altering the splicing of pyruvate kinase (PKM) in leukemia." (PMID 41214140, 2026).
pancreatic ductal adenocarcinoma (20 papers, 2016 to 2026). An infiltrating adenocarcinoma that arises from the epithelial cells of the pancreas. "A previous study identified novel genes associated with poor prognosis in pancreatic ductal adenocarcinoma by carrying bioinformatics analysis on PKM and PPARG." (PMID 33942483, 2021). "For example, pancreatic ductal adenocarcinoma (PDAC) cells subjected to prolonged gemcitabine exposure upregulated a critical splicing factor that regulates PKM splicing known as polypyrimidine-tract binding protein (PTBP1), causing PKM2 isoform overexpression." (PMID 40282556, 2025).
triple-negative breast carcinoma (17 papers, 2017 to 2026). An invasive breast carcinoma which is negative for expression of estrogen receptor (ER), progesterone receptor (PR), and human epidermal growth factor receptor 2 (HER2). "In triple-negative breast cancer (TNBC), the amino acid transporter SLC7A5 downregulates miR-152 and activates the E2F1/PTBP1 signaling axis, promoting alternative splicing of PKM pre-mRNA toward the PKM2 isoform." (PMID 40842995, 2025). "Pyruvate kinase M1/2 (PKM) converts phosphoenolpyruvate to pyruvate and can inhibit the expansion and metastasis of triple-negative breast cancer cells." (PMID 37180167, 2023).